FHL1 (four and a half LIM domains 1)
Diseases named in the same sentence as FHL1 in open-access papers (continued):
Sharing a sentence is not in itself a finding about the gene and the disease.
Emery-Dreifuss muscular dystrophy (13 papers, 2013 to 2024). Emery-Dreifuss muscular dystrophy (EDMD) is characterized by muscular weakness and atrophy, with early joint contractures and cardiomyopathy. "Mutations in FHL1 cause several forms of X-linked dominant disorders, including Emery-Dreifuss muscular dystrophy (EDMD), X-linked scapuloperoneal myopathy, reducing body myopathies, rigid spine syndromes and sometimes hypertrophic cardiomyopathy." (PMID 39501809, 2024). "Loss of emerin, mutations in emerin-associated proteins (A-type lamins, nesprin-1, nesprin-2, LUMA) or mutations in transcription factor FHL1 are all genetically linked to Emery-Dreifuss muscular dystrophy (EDMD) (Meinke, Nguyen & Wehnert, 2011)." (PMID 24010014, 2013). "FHL3 is closely related to FHL1 that is directly linked to Emery-Dreifuss muscular dystrophy." (PMID 29912636, 2018). "FHL1 is a well established, “strong” cause of Emery Dreifuss muscular dystrophy (EDMD) and may also cause isolated HCM." (PMID 27446933, 2016). "Mutations in FHL1 have been observed in patients with ‘Emery-Dreifuss muscular dystrophy’ (EDMD)." (PMID 28877219, 2017). "A number of genetic studies linked FHL1 missense mutations to congenital myopathies previously recognized by particular structural features, including Reducing body myopathy (RBM) and Emery-Dreifuss Muscular Dystrophy (EDMD)." (PMID 28444561, 2017). "We thereby report a novel mutation variant in FHL1 structure, associated with HCM and type 6 Emery-Dreifuss muscular dystrophy (EDMD)." (PMID 32993534, 2020). "As mutations in the FHL-1 gene have been previously linked to another laminopathy, Emery-Dreifuss muscular dystrophy (EDMD), we investigated FHL-1 protein levels in total fibroblast extracts." (PMID 25510262, 2015). "It was also demonstrated that FHL1-deficient mice were less susceptible to CHIKV infection, and more importantly, virus replication was greatly impaired in fibroblasts and myoblasts derived from Emery-Dreifuss muscular dystrophy (EDMD) patients, in which the FHL1 gene was mutated." (PMID 35401487, 2022). "In addition to XMPMA, mutations in the FHL1 gene have been associated with other four clinically distinct human myopathies, including reducing body myopathy (RBM), X-linked dominant scapuloperoneal myopathy (SPM), Emery-Dreifuss muscular dystrophy (EDMD), and rigid spine syndrome (RSS)." (PMID 27443559, 2016).
hypertrophic cardiomyopathy (10 papers, 2013 to 2025). A condition in which the myocardium is hypertrophied without an obvious cause. "Abnormal expression of Fhl1 is associated with several diseases such as skeletal muscle disease, reductive myopathy, hypertrophic cardiomyopathy, and viral infections (chikungunya and cashmere)." (PMID 41011134, 2025). "Experiments using FHL1 knockout mice crossed into two models for hypertrophic cardiomyopathy serve as an example, whereby the underlying pathology plays a major role on the effect of FHL1 removal." (PMID 34745373, 2021). "This case report highlights the importance of multimodality diagnostic approach in a patient with a neuromuscular disorder and associated hypertrophic cardiomyopathy by identifying a novel mutation variant in FHL1 gene." (PMID 32993534, 2020). "Isolated hypertrophic cardiomyopathy due to pathogenic FHL1 mutations has been reported." (PMID 32659924, 2020). "Pathological mutations in the N2Bus3 region of titin that have been associated with the development of hypertrophic cardiomyopathy were shown to affect binding of FHL2 and FHL1." (PMID 34745373, 2021). "Mutations in distal exons that encode the third and fourth LIM domains, as well as frameshift mutations leading to reduced FHL1 expression, are associated with non-reducing body disorders such as hypertrophic cardiomyopathy and EDMD." (PMID 39501809, 2024). "However, FHL1 expression is increased in idiopathic pulmonary arterial hypertension patients, in patients with LV hypertrophy and hypertrophic cardiomyopathy, as well as in mice with agonist, pressure or volume-overload cardiac hypertrophy." (PMID 34745373, 2021). "Many reports later described additional mutations that broadened the phenotypic spectrum further, adding Emery–Dreifuss muscular dystrophy (EDMD) and hypertrophic cardiomyopathy (HCM) with no or minimal musculo-skeletal involvement to the clinical presentations of FHL1 mutations." (PMID 28444561, 2017). "Mice lacking Fhl1 reversed the development of hypertrophic cardiomyopathy, which is induced by biomechanical stress." (PMID 24265776, 2013). "Mice lacking Fhl1 were protected from the onset of hypertrophic cardiomyopathy, which is normally induced by biomechanical stress, whereas transgenic expression of Fhl1 in mice promoted skeletal muscle hypertrophy." (PMID 24265776, 2013).
muscular dystrophy (10 papers, 2011 to 2026). Muscular dystrophy (MD) refers to a group of more than 30 genetic diseases characterized by progressive weakness and degeneration of the skeletal muscles that control movement. "The strong association with DMD in our data was all the more striking because yet another gene implicated in muscular dystrophy—FHL1—was identified in the European female sample." (PMID 28877219, 2017). "Several mutations in the human FHL1 gene are associated with severe or less severe types of hereditary muscular dystrophies and myopathies." (PMID 22053194, 2011). "FHL1 acts as a scaffolding protein during muscle assembly and promotes myoblast differentiation, while being implicated in the pathogenesis of several myogenic conditions, including muscular dystrophy and the tropical disease chikungunya." (PMID 34066295, 2021). "Mutations in FHL1 (previously called skeletal muscle LIM protein 1) cause distinct types of muscular dystrophies e.g. XMPMA, which may be associated with cell cycle alterations of myoblasts." (PMID 22053194, 2011). "Fhl1 is most abundant in skeletal muscle, and abnormalities in the Fhl1 gene have been identified as pathogenic factors in various muscle disorders, such as X-linked myopathy, myofibrillar myopathy, muscular dystrophy, inflammatory myopathy and reducing body myopathy." (PMID 40424254, 2025). "The current study is the first to exploit this important regulatory function for FHL1 in controlling myoblast fusion in a muscular dystrophy model, revealing partial amelioration of the FSHD disease phenotype." (PMID 25695429, 2015). "Importantly, our study reveals that FHL1, a positive regulator of muscle hypertrophy and myoblast fusion, reduces muscle wasting and improves the muscular dystrophy phenotype observed in FRG1 mice by rescuing the FRG1-induced myoblast fusion defect." (PMID 25695429, 2015). "Therefore, increased FRG1 expression may contribute to a muscular dystrophy phenotype resembling FSHD by impairing myoblast fusion, a defect that can be rescued by enhanced myoblast fusion via expression of FHL1." (PMID 25695429, 2015).
pulmonary hypertension (8 papers, 2010 to 2024). Increased pressure within the pulmonary circulation due to lung or heart disorder. "In this regard, FHL-1 has been implicated in dysregulated hypertrophic signaling in pulmonary arterial smooth muscle cells leading to pulmonary hypertension." (PMID 31980934, 2020). "Four and a half LIM domains 1 (Fhl1 or Slim1) is a member of this family and has likewise been implicated in skeletal muscle development as well as in the pulmonary vascular remodeling underlying pulmonary hypertension." (PMID 20525254, 2010). "FHL1 knockdown arrested pulmonary artery SMCs at the G1 phase and dampened cell proliferation in hypoxia-induced pulmonary hypertension." (PMID 36184652, 2022). "The cytoskeletal signaling protein four and-a-half LIM domains 1 (FHL-1) has recently been identified as a novel key player in pulmonary hypertension as well as in left heart diseases." (PMID 31980934, 2020). "miR-206 has exhibited its regulation of fibroblast growth factor, Hmgb3 and HIF-1α/Fhl-1 pathways in amyotrophic lateral sclerosis, muscle regeneration and pulmonary hypertension, respectively." (PMID 25816284, 2015). "In cultured hypoxic pulmonary artery smooth muscle cells (PASMCs), miR-206 promotes the Hypoxia-induced pulmonary hypertension though the HIF-1a/Fhl-1 pathway." (PMID 24887070, 2014). "Until now, the role of Fhl1 in vascular diseases has only been described in pulmonary hypertension." (PMID 39639552, 2024).
X-linked myopathy with postural muscle atrophy (8 papers, 2011 to 2023). X-linked myopathy with postural muscle atrophy is a rare progressive muscular dystrophy characterized by an adult-onset scapulo-axio-peroneal myopathy. "FHL1 is also linked to other myopathies such as X-linked myopathy with postural muscle atrophy (XMPMA) and deletion in mice leads to muscle hypertrophy." (PMID 28214269, 2017). "For example, over-expression of FHL1 leads to muscle hypertrophy and patients with mutations in FHL1 have a range of myopathic conditions including X-linked myopathy with postural muscle atrophy (XMPMA)." (PMID 26504741, 2015). "Mutations in the FHL1 gene are causative for several types of hereditary myopathies including X-linked myopathy with postural muscle atrophy (XMPMA)." (PMID 22053194, 2011). "Moreover, FHL1 has been linked to other myopathies such as X-linked myopathy with postural muscle atrophy (XMPMA) via its signal transduction function." (PMID 31862442, 2020).
gastric cancer (7 papers, 2014 to 2025). A primary or metastatic malignant neoplasm involving the stomach. "Lower FHL1 expression was positively associated with lower degree of differentiation, higher lymph node metastasis, and greater invasive potential of gastric cancer." (PMID 32587768, 2020). "In contrast, the expression of Fhl1 is upregulated in cancers such as laryngeal carcinomas, gastric signet ring cell carcinoma, lung adenocarcinoma, gastric cancer, acute promyelocytic leukemia, and glioblastoma, among others." (PMID 41011134, 2025). "The effects of FHL1 on the invasion and metastasis of gastric cancer were further confirmed in vitro." (PMID 32587768, 2020). "Overexpression of FHL1 in the human gastric cancer cell line, MKN45, significantly inhibited invasiveness and metastatic ability, as determined using the Transwell assay." (PMID 32587768, 2020). "While CCDC43 functions as an oncogene in gastric cancer, FHL1 promotes apoptosis of GC cells." (PMID 40678420, 2025). "Reduced FHL1 expression may thus contribute to enhanced tumor aggressiveness, correlating with significantly shorter survival in primary gastric cancer patients." (PMID 32587768, 2020). "In gastric cancer, CCDC43 has been shown to colocalize with four and a half LIM domain protein 1 (FHL1), but these two proteins act as antagonists." (PMID 40678420, 2025). "Although there have been no reports showing the role of CCDC43 in cell death in the context of HCC, it was previously shown in a gastric cancer study that CCDC43 acts opposite to four and a half LIM domains 1 (FHL1), which in turn promotes cell death." (PMID 37614502, 2023).
rigid spine syndrome (7 papers, 2014 to 2024). "In patients affected by rigid spine syndrome (RSS) with a mutation in the FHL1 gene, Bonaldo’s group described for the first time the activation of the pathway involved in the selective removal of aggresomes." (PMID 37176163, 2023). "Mutations of the FHL1 gene have been associated with diverse chronic myopathies including reducing body myopathy, rigid spine syndrome (RSS), and Emery–Dreifuss muscular dystrophy." (PMID 25191266, 2014). "Differentiation from other early-onset conditions involving rigid spine syndrome caused by SELENON, FHL1, LMNA, and others is crucial." (PMID 39468638, 2024). "To date, aggrephagy has been investigated only in a limited number of diseases, reveling a pathological role in a case of FHL1-rigid spine syndrome and in a small case series of sIBM, PLIN4-related myopathy, myotilinopathies and desminopathies and oculopharyngeal muscular dystrophy." (PMID 37176163, 2023).
hepatic carcinoma (6 papers, 2014 to 2023). "For example, the knockdown of FHL1 significantly enhanced the sensitivity of paclitaxel in hepatic carcinoma cells." (PMID 36752296, 2023). "FHL1 additionally inhibits anchorage-dependent and -independent growth of human hepatocellular carcinoma cells, both in vitro and in vivo." (PMID 32587768, 2020). "Thus, CK1δ and Smad4 are required for FHL1-mediated inhibition of hepatocellular carcinoma (HCC) cell growth." (PMID 32587768, 2020). "Subsequently, FHL1 was shown to block HIF1α-HIF1β heterodimerization for regulation of HIF1 activity in hepatocellular carcinoma cells, leading to decreased promoter activity and expression of vascular endothelial growth factor (VEGF), an important target gene of HIF1α54." (PMID 32587768, 2020). "Recently, it has been shown that FHL1, FHL2, and FHL3 physically and functionally interact with Smad2, Smad3, and Smad4, important regulators of cancer development and progression, and inhibit human hepatoma cell growth in vitro and in vivo." (PMID 24690879, 2014).
myofibrillar myopathy (6 papers, 2014 to 2025). "The same FHL1 mutation was previously reported in a family with RBM phenotype and in two patients with RBs and myofibrillar myopathy." (PMID 25191266, 2014).
colorectal tumors (5 papers, 2014 to 2024). "For example, miR-410 exhibited upregulation in liver and colorectal tumors, thereby promoting the progression and invasion of cancerous cells via directly/indirectly regulating tumor-suppressor gene FHL1." (PMID 38238515, 2024). "In liver and colorectal tumors, upregulated miR-410 increased the tumor cell growth by silencing FHL1 tissues/cell lines." (PMID 33005638, 2020).
oral cancer (5 papers, 2018 to 2025). "Studies in oral cancer and bladder cancer have also found that reduced expression of FHL1 promotes tumor progression and is associated with poor prognosis 10,23." (PMID 34335951, 2021). "Similarly, down-regulation of FHL1 was associated with a poor prognosis of esophageal squamous cell carcinoma and oral cancer." (PMID 36752296, 2023). "The expression of Fhl1 is downregulated in several cancers such as lung, prostate, breast, ovarian, colon, thyroid, brain, kidney, liver, and skin (melanoma), as well as oral cancers." (PMID 41011134, 2025).
age-related macular degeneration (4 papers, 2015 to 2022). Age-related loss of vision in the central portion of the retina (macula), secondary to retinal degeneration. "The discovery that FHL-1 is the predominant regulator on Bruch’s membrane, a critical site for the onset and progression of age-related-macular degeneration (AMD), showed that FHL-1 is essential for complement regulation." (PMID 33178228, 2020). "One particular variant of FH/FHL-1 (termed 402H; that has a histidine at residue 402 in CCP7) is associated with an increased risk of age-related macular degeneration (AMD), a common cause of blindness in developed nations, and requires a high level of HS sulfation for its binding." (PMID 25699044, 2015).
Arrhythmia (4 papers, 2016 to 2025). Any cardiac rhythm other than the normal sinus rhythm. "Mutations in the FHL1 gene have been also associated with arrhythmias, HCM and dilated cardiomyopathy in several patients affected by skeletal muscle disorders as well." (PMID 27443559, 2016).
bladder cancer (4 papers, 2018 to 2024). "Also, FHL1 gene silencing was associated with cell proliferation and invasion in human bladder cancer cells." (PMID 39519555, 2024). "Regarding FHL1 expression in tumors, studies have shown that FHL1 is downregulated in various tumors, such as breast, lung, oral and bladder cancer 20-22." (PMID 34335951, 2021).
colorectal cancer (4 papers, 2014 to 2025). A primary or metastatic malignant neoplasm that affects the colon or rectum. "We also explored the associations between FHL1 mRNA expression level and the clinicopathological features of these 40 colorectal cancer patients." (PMID 34335951, 2021). "All these results indicated that FHL1 expression was downregulated in colorectal cancer tissues and that this was associated with a worse clinical outcome." (PMID 34335951, 2021). "The results showed that both FHL1 mRNA and protein expression levels were downregulated in the five colorectal cancer cell lines compared with NCM460." (PMID 34335951, 2021). "Compared with that in adjacent tissues, the expression of FHL1 mRNA and protein in colorectal cancer tissue was significantly downregulated, and it was correlated with TNM stage and lymph node metastasis in CRC patients." (PMID 34335951, 2021). "Taken together, these data indicate that FHL1 inhibits the proliferation of colorectal cancer cells by regulating the Wnt/β-catenin signaling pathway." (PMID 34335951, 2021). "Next, we selected 5 colorectal cancer cell lines and 1 normal intestinal epithelial cell line and detected the gene and protein expression levels of FHL1 in each." (PMID 34335951, 2021). "In this study, we revealed the relationship between FHL1 and the Wnt/β-catenin signaling pathway by in vitro experiments on colorectal cancer cells." (PMID 34335951, 2021). "We report that miR-410 is upregulated in colorectal cancer and hepatocarcinoma and that miR-410 can decrease FHL1 protein levels both directly by targeting the FHL1 3'UTR and indirectly by promoting the up-regulation of DNA methylases." (PMID 25272045, 2014). "Furthermore, we explored the functional role of FHL1 in colorectal cancer tumorigenesis by transfecting cells with siRNA or overexpression plasmids." (PMID 34335951, 2021). "FHL1 gene expression in colorectal cancer tissues was also significantly downregulated." (PMID 34335951, 2021). "Before we explored the functional role of FHL1 in colorectal cancer tumorigenesis, we measured the expression levels of FHL1 mRNA and protein in 5 CRC cell lines, namely, HCT116, HT29, LOVO, SW620 and SW480, as well as in NCM460, a normal colon epithelial cell line." (PMID 34335951, 2021). "Our study evaluated the expression of FHL1 in colorectal cancer." (PMID 34335951, 2021). "Moreover, we showed that FHL1 inhibited the proliferation of colorectal cancer cells by negatively regulating the Wnt/β-catenin signaling pathway." (PMID 34335951, 2021). "In colorectal cancer, FHL1 has been reported to be a tumor suppressor gene by negatively regulating the Wnt/β-catenin signaling pathway." (PMID 40831931, 2025). "The findings here within indicate, for the first time, that miR-410 may serve as a regulator of FHL1 expression through direct targeting of its 3'UTR and indirect regulation of its methylation in human colorectal cancer and hepatocarcinoma." (PMID 25272045, 2014).
dilated cardiomyopathy (4 papers, 2016 to 2024). Cardiomyopathy which is characterized by dilation and contractile dysfunction of the left and right ventricles. "A cardiac phenotype often manifests as hypertrophic or dilated cardiomyopathy and is the most serious symptom in FHL1-induced EDMD patients." (PMID 34745373, 2021). "FHL1 was also not upregulated upon loss of FHL2 at baseline; however, it becomes the predominant FHL protein induced by TAC and in a model of dilated cardiomyopathy." (PMID 34745373, 2021).
lung adenocarcinoma (4 papers, 2022 to 2025). A carcinoma that arises from the lung and is characterized by the presence of malignant glandular epithelial cells. "We investigated the influences of FHL1 on cell functions as well as its molecular mechanisms in lung adenocarcinoma (LUAD) cells." (PMID 36017148, 2022). "Kaplan–Meier Plotter analysis showed that lung adenocarcinoma patients with positive ATCR2, FHL1, RAB27B, and RAP1B expression had observably longer overall survival than patients with negative expression (P < 0.05)." (PMID 36404333, 2022).
melanoma (4 papers, 2018 to 2025). A malignant, usually aggressive tumor composed of atypical, neoplastic melanocytes. "FHL1 expression was found downregulated in melanoma and leukemia cell lines." (PMID 29454310, 2018).